APC (APC regulator of Wnt signaling pathway)
Diseases named in the same sentence as APC in open-access papers (continued):
Sharing a sentence is not in itself a finding about the gene and the disease.
adenoma (continued). "Thus, chromosomal aneuploidies affecting chromosomes 7, 13, and 20q (all chromosomal gains) cooperate with APC mutations in the progression from adenoma with low-grade dysplasia to adenoma with high-grade dysplasia." (PMID 33066148, 2020). "In this view, APC mutation might lead to autocatalytic expansion of crypts and produce a large mass of crypts, a.k.a. adenoma morphogenesis." (PMID 32079164, 2020). "Adenomas in FAP patients show loss of the 2nd wild-type APC allele." (PMID 32079164, 2020). "This suggests that BRAF and APC mutations are mutually exclusive in conventional adenomas." (PMID 32384699, 2020). "In humans, abnormal expression of Wnt in ISCs promotes adenoma formation, while deletions in mouse ISCs of the tumor suppressor adenomatous polyposis coli gene APC triggers the initial step of colon-adenoma formation, underlying the relevance of both mutations in this malignancy." (PMID 30881374, 2019). "Overall, our work supports a mechanism where CTBP1 regulates CNOT3 and that overall CNOT3 perturbation could work in concert with germline APC mutations in advancing adenomas to a more transformed state prior to progression to adenocarcinoma." (PMID 31231471, 2019). "APC is widely assumed as the only relevant gene mutated in early adenomas, but it is only recently that next-generation sequencing of colon adenomas have resulted in data to confirm this long-standing hypothesis." (PMID 31231471, 2019). "Recently, ACF were identified in the proximal colons of about 40% of individuals undergoing high-resolution chromoendoscopy and more frequently in patients with synchronous proximal adenomas; somatic mutations of APC, BRAF, KRAS, NRAS and ERBB2 were detected in 37% of proximal ACF." (PMID 29652830, 2018). "Hence, the monoclonal conversion of the stem cell niche by the progeny of the tumor-originating cell with loss of the APC gene induces the establishment of an adenoma on the tissue scale." (PMID 30687642, 2018). "This theory is supported by the fact that small adenomas, advanced adenomas and carcinomas have almost the same frequency of mutations in the APC gene, and may explain why we saw all mutations in the APC gene as shared." (PMID 30029640, 2018). "Therefore, following APC loss, CtBP1 contributes to adenoma initiation as a first step, whereas KRAS activation and β-catenin nuclear localization promote adenoma progression to carcinomas as a second step." (PMID 29652830, 2018). "APC is the gene most frequently mutated in conventional colon adenomas; four genes recurrently mutated in adenomas CTNNB1 (catenin-β1), KRTAP4-5 (keratin-associated protein 4–5), GOLGA8B (golgin A8 family member B) and TMPRSS13 (transmembrane protease, serine 13) had the oncogene pattern." (PMID 29652830, 2018). "However, the monoclonal origin of CRC has been brought into question by genetic analysis of individual colonic crypts of benign adenomas, in which polyclonality of driver events, including distinct mutations in APC and KRAS, has been identified." (PMID 30166531, 2018). "About 60% of adenomas and carcinomas harbor mutations in the APC gene." (PMID 30256815, 2018). "Loss of APC heterozygosity in these animals results in adenoma formation through out the GI tract." (PMID 28650985, 2017).
adenoma (continued). "More recently, Boman and Fields found that APC-mutation-induced changes in the counter-current-like mechanism, triggering expansion of proliferative populations, driving crypt fission premalignant changes and adenoma development." (PMID 28273142, 2017). "Furthermore, we identified a protective role of genetic deficiency of LMP7 in spontaneous tumorigenesis upon loss of the APC gene, as well as for the establishment of adenomas and/or adenocarcinomas in inflammation-mediated tumor models." (PMID 28881611, 2017). "In most human adenomas and CRCs, Wnt pathway defects, most commonly APC inactivating mutations, lead to dysregulated β-catenin/T cell factor (TCF) transcription with resultant activation of genes normally restricted to intestinal stem cells in many neoplastic cells in the lesions." (PMID 28072391, 2017). "Of the eight MAP adenomas, five had bi‐allelic nonsense APC mutations." (PMID 26414517, 2016). "The second starting point is mutation in APC leading to the formation of small tubular adenomas." (PMID 27276710, 2016). "In FAP, adenomas may develop following somatic inactivation of the wild‐type allele of APC, an event that is thought to be among the earliest somatic changes occurring during tumourigenesis in these patients." (PMID 26414517, 2016). "Since APC mutations are detected very early in the adenoma-carcinoma sequence, the APC protein has been suggested to act as a "gatekeeper" of colorectal carcinogenesis, which means that functional loss of APC is a prerequisite for the progression towards malignancy." (PMID 28010732, 2016). "This process is referred to as the adenoma-carcinoma sequence that occurs through a multistep mechanism associated with mutations in the adenomatous polyposis coli (APC) gene and in components of the mitogen-activated protein kinase (MAPK) signaling pathway, such as KRAS2." (PMID 27194068, 2016). "However, if so, why was intestine-specific deletion of FAK alone sufficient to cause complete abrogation of adenoma formation in APC-mutant mice ?" (PMID 26274564, 2015). "Considering that a significant number of intestinal adenomas has also been reported to arise without the loss of heterozygosity of the APC gene and these adenomas are often polyclonal, our results supports an APC-independent mechanism of β-catenin stabilization during 56Fe-irradiated tumorigenesis." (PMID 26500891, 2015). "In the first phase, inactivation of the APC gene causes the development of adenomas." (PMID 25945086, 2015). "The wild type APC allele is somatically inactivated in adenomas arising in those with FAP." (PMID 26528816, 2015). "Similarly, the links between the underlying APC, β-cat and E-cadherin (E-cad) biochemistry and adenoma formation are still unclear." (PMID 26087250, 2015). "In familial or sporadic CRC, the mutational inactivation of APC, a negative regulator of the Wnt/β-catenin signaling pathway, appears to be an immediate-early event, occurring in over 90% of cancers and triggering the formation of focal early adenomas." (PMID 24920319, 2014). "Another recent study demonstrated that myeloid cells, particularly Gr1+ but also F4/80+ and CD11b+ cells, respond to intestinal microbiota by secreting IL-23, which is particularly important in the development of adenomas in the colon of mice with an APC mutation." (PMID 24866282, 2014). "Moreover, somatic mutations in the APC gene are an early event in colorectal tumorigenesis and in fact somatic mutations are present in adenomas less than 1 mm in size." (PMID 24790607, 2014).
adenoma (continued). "In FAP syndrome, an autosomal-dominant genetic disorder characterized by the development of hundreds to thousands adenomas in the colorectum during adolescence and young adulthood, there is a germline mutation of the APC gene that has been identified in 60%–80% of families with FAP." (PMID 23965959, 2013). "It should be noted that the remaining cases of adenomas and adenocarcinomas may have mutations in other residues of APC and FBXW7." (PMID 23301059, 2013). "Therefore, based on our mechanism, changes in APC and WNT that are due to APC mutation alter regulation of the crypt cycle, cause abnormal crypt fission, and drive adenoma development." (PMID 24224156, 2013). "The lower APC mutation rate in flat adenomas compared to polypoid adenomas suggests that disruption of the Wnt-pathway may occur via different mechanisms in these two phenotypes." (PMID 22848674, 2012). "Moreover, comparing adenomas and HPs/SSAs in MAP patients, APC mutations were only detectable in adenomas, indicating two possible tumor pathways, one leading to adenomas via APC mutations, and the other leading to HPs/SSAs via KRAS activation." (PMID 22876359, 2012). "Four samples contained a double mutation in APC, i.e. three flat adenomas and one polypoid adenoma." (PMID 22848674, 2012). "After stratification for anatomical location the difference in APC mutation frequency between flat adenomas and polypoid adenomas persisted for the distal colon with 61.7% (37/60) of polypoid adenomas showing APC mutations compared to 31.0% (9/29) of flat adenomas." (PMID 22848674, 2012). "It has been suggested APC mutations may be a rate-limiting event in the development of most adenomas, and both alleles are often inactivated by this point." (PMID 22997602, 2012). "At the same time we observed fewer APC mutations in flat adenomas, compared to polypoid adenomas." (PMID 22848674, 2012). "In this family, we suggested that the promoter hypermethylation observed in adenomas and carcinomas from the proband may inactivate the second allele of APC and manifest the severe phenotype." (PMID 22164339, 2011). "APC mutations were only detected in 10% of the serrated lesions but in 34% of the adenomas." (PMID 24212608, 2010). "However, they become frequent in colorectal adenomas as demonstrated by the fact that in the present study a mutated APC gene was detected in one third of the adenoma samples analyzed." (PMID 24212608, 2010). "However, the only significant combination was APC.1-APC.2 already found, showing that MYH does not provide any additional contribution to the association between APC and adenomas." (PMID 19888426, 2009). "However, another study (N=59) showed that almost 70% of patients with an AFAP-like phenotype (10-100 adenomas) had a germline APC mutation." (PMID 19506731, 2008). "Similarly, one study of patients with an AFAP-like phenotype (3-100 adenomas), found that merely about 10% of these patients had inherited germline APC mutations." (PMID 19506731, 2008). "Mutations in the APC gene have been detected in the majority of adenoma and CRC cases." (PMID 16545110, 2006). "APC mutations were detected in 55% of the adenomas (25/45) and in 51% of the CRC tumors (45/88)." (PMID 16545110, 2006). "Adenomas, smoking history and APC truncation mutation status." (PMID 16545110, 2006). "However, we have been able to show for the first time loss of the D5S43 locus on chromosome 5 in adenomas from three patients, two of whom had the precancerous condition adenomatous polyposis coli (APC)." (PMID 2539177, 1989). "Similarly, the adenomas in patient P3 shared three mutations, including one in APC gene (E1536fs)." (PMID 39554798, 2024). "In addition to the most prevalent genetic alteration—APC mutation leading to chromosomal instability in the classic adenoma–carcinoma sequence—two more-significant but less-prevalent pathways have been described, microsatellite instability and DNA methylation in CpG islands." (PMID 39456841, 2024).
adenoma (continued). "In the normal population, it is postulated that most CRCs arise through biallelic somatic APC mutations initiating an adenoma that may develop into a carcinoma as a result of acquiring additional driver mutations, and less often through an initiating mutation in CTNNB1." (PMID 38741120, 2024). "However, in human CRC, although Wnt activation by APC mutations sufficiently activates Wnt signaling, multiple other mutations in the Wnt pathway are observed in the adenomas in both familial adenomatous polyposis patients and sporadic adenomas, and the resulting sporadic carcinomas." (PMID 35975243, 2022). "Hence, a total of 13 truncating APC variants were identified in the adenomas." (PMID 34843512, 2021). "Interestingly, pathogenic somatic APC variants were found in all but one adenoma." (PMID 34843512, 2021). "Moreover, this may explain why increased abundance of F. nucleatum occurs already during the first phase of adenoma, as the APC mutation is among the first molecular alterations that arise in the epithelium while it is in transition to become adenoma." (PMID 33013813, 2020). "High-confidence targets additionally validated in mouse adenomas included 16 increased and 9 decreased in expression following APC loss, indicating that chromatin-associated APC may antagonize canonical WNT signaling at both WNT-activated and WNT-repressed targets." (PMID 30131849, 2018). "However, histopathological analyses have also suggested a stem cell route through to the identification of monocryptal adenomas in patients who develop familial adenomatous polyposis due to a germline mutation in APC, supporting the ‘bottom-up’ model of intestinal tumourigenesis." (PMID 28622298, 2017). "Importantly, the APC-deficient cysts are highly reminiscent of cysts commonly present in adenoma confirming that organoids in culture recapitulate features of tissue in situ and provide an excellent model system to study changes in polarity during tumour progression." (PMID 24062584, 2013). "Interestingly, we found that loss of chromosome 5q is significantly more frequent in flat adenomas compared to polypoid adenomas, which also may affect APC located within this loss." (PMID 22848674, 2012). "To evaluate the hypothesis that cigarette smoking is associated with adenoma and carcinoma development and further to investigate whether this association is due to mutations in the APC gene, we used a study population consisting of 133 cases (45 adenomas and 88 carcinomas) and 334 controls." (PMID 16545110, 2006). "To identify the possible differences between different adenomas that either predispose to cancer or result in benign growths, we compared variations in gene expression between different adenomas and normal mucosa from the same patient with a germline mutation in the APC gene." (PMID 15982419, 2005). "DNA from 63 adenomas (31 polypoid, 17 superficial elevated, 15 superficial depressed), 66 submucosally invasive carcinomas (47 polypoid, 19 non-polypoid) and 34 advanced carcinomas were examined for K- ras codon 12 point mutations and APC mutations in the mutation cluster region." (PMID 10638959, 2000). "Loss-of-function mutations in the tumor suppressor gene APC initiate neoplastic transformation, while subsequent activating mutations in the oncogene KRAS are frequently associated with the progression from benign adenoma to dysplastic adenocarcinoma." (PMID 41294868, 2025). "They observed that certain adenomas shared methylation profiles with cancers, including intergenic and intragenic CpG changes and driver mutations in KRAS and APC, suggesting that epigenetic reprogramming begins early and persists through progression." (PMID 40806210, 2025). "For the autosomal dominant genes, somatic second hits via somatic mutations or loss of heterozygosity inactivating the wildtype allele, have been demonstrated for APC- and AXIN2-related adenomas and CRCs." (PMID 40237887, 2025).
adenoma (continued). "Somatic or genetic mutations in the adenomatous polyposis coli (APC) gene are frequently detected in early carcinogenesis in the development of CRC and are detected in 70% of patients with adenoma." (PMID 40142219, 2025). "Still, the two shared APC variants in T1-T4 combined with the POLD1 variant in T3 and T4, and the fact that the adenomas were removed during four consecutive EGDs suggests a recurrence, so clonal relationship." (PMID 40956995, 2025). "The tumors observed in this model resembled adenocarcinomas originating from the adenoma-carcinoma sequence in APC mut mice." (PMID 41285904, 2025). "We explored molecular alterations using target sequencing in the early phase of adenoma-carcinoma sequences and analyzed the APC gene alterations in these early lesions by comparing colorectal neoplasms in FAP patients with sporadic colonic neoplasms." (PMID 41488735, 2025). "In summary, the risk factors associated with cfDNA‐positive adenomas included a mixture of CRA with adenocarcinoma, a large CRA size (exceeding 2 × 2 cm), and the copresence of APC and KARS mutations." (PMID 39554798, 2024). "For 21 adenomas with both WES and WTS data, the latter was used to confirm the APC, PIGA, and KRAS mutations identified by WES, with concordant findings in all cases." (PMID 38546397, 2024). "Although the function of APC initiates the adenoma-carcinoma transition in the majority of CRCs through constitutive activation of Wnt/beta-catenin signaling, the APC gene also represents a candidate chromosome instability (CIN) gene in CRC." (PMID 39021676, 2024). "The results of the sequencing analysis in the patient with the large HGD adenoma, indicated that APC (Adenomatous Polyposis Coli), KIT, and possibly JAK3 were the most likely early drivers of tumorigenesis in these patients." (PMID 39507544, 2024). "The adenoma-carcinoma pathway accounts for approximately 70% of CRC and is typically associated with the early acquisition of APC mutations, which are reported in 70–80% of resulting adenocarcinomas." (PMID 39340753, 2024). "Very rarely are APC mutations found in CRC arising from the serrated pathway, with a recent study reporting that truncating APC mutations occur in only 8% of serrated CRC, compared to the 70–80% of adenoma-carcinoma cases." (PMID 39340753, 2024). "These patients are born with a germline mutation affecting one APC allele, spontaneous loss of the second wild-type allele leads to enhanced WNT signalling and adenoma formation at an early age." (PMID 39332495, 2024).